IL9 (interleukin 9)
Diseases named in the same sentence as IL9 in open-access papers (continued):
Sharing a sentence is not in itself a finding about the gene and the disease.
eosinophilia (22 papers, 2005 to 2024). "The association of IL-9 and IL-22 with eosinophilia, and the decrease in these two cytokines with cows’ milk elimination, suggests that they both play a role in the symptoms observed in CMA and may be important targets for future interventions." (PMID 28934137, 2017). "An association between IL-9 expressing cells and eosinophilia has also been described." (PMID 15840176, 2005). "These cells are responsible forinterleukin (IL) 4, IL-5, IL-9, and IL-13 as well asabnormal immunoglobulin production, i.e., atopy,eosinophilia, and mast cell enlargement." (PMID 37345397, 2023). "Th2 cytokines such as IL-4, IL-13, and IL-9 promote eosinophilia by regulating local IL-5, eotaxin synthesis, and/or inhibiting IFN-gamma production." (PMID 35805534, 2022). "IL-5 and IL-9 are critical for promoting tissue eosinophilia and mast cell hyperplasia, whereas IL- 13 stimulates mucus production by goblet cells and AHR." (PMID 33114551, 2020). "The pro-allergic function of Irf1−/− Th9 cells was ameliorated by treatment with IL-9-neutralizing antibodies as determined by decrease in eosinophilia, in the numbers of mucus-producing cells and in inflammation." (PMID 28497800, 2017). "Anti-IL-9 significantly reduced bone marrow eosinophilia, primarily by decrease of newly produced (BrdU+) and mature eosinophils." (PMID 15823208, 2005). "In two separate mouse model studies of allergen-induced asthma, administration of neutralising anti-IL-9 antibodies reduced eosinophilia, BHR, airway damage and IgE." (PMID 15840176, 2005). "IL-9 promotes allergic responses, including IgE production and eosinophilia." (PMID 39439788, 2024). "Importantly, the group of mice that received IL-1β-rescued Th9 cells with in vivo anti-IL-9 blockade exhibited reduced levels of inflammation indicating that both lung eosinophilia and airway inflammation are IL-9-dependent." (PMID 36389679, 2022). "When assessed in combination with eosinophilia (i.e. > 400 cells/μl) and absolute WBC count, a panel comprising eosinophilia, IL-9 and CCL3 was highlighted as having 87.6% AUC (85.3% SP–87.5% SE), as soon as two out of the three variables are above (or below) their respective cut-offs." (PMID 33059754, 2020). "These cells produce IL-9 and inhibit Th2 cytokine production and promote eosinophilia." (PMID 27973603, 2016). "Previous studies have also demonstrated that eosinophilia occurs between the 5th and 7th weeks after exposure to the parasite and may be induced by Th2 cytokines, such as IL-4, IL-10, IL-13, IL-9, and especially IL-5." (PMID 23401741, 2013). "Interestingly, after allergen exposure an anti-IL-9 antibody significantly reduces bone marrow eosinophilia in an animal model primarily by decreasing newly produced and mature eosinophils." (PMID 18315837, 2008). "We cannot exclude the possibility that even higher doses of the neutralizing monoclonal IL-9 antibody could have been more effective in attenuating eosinophilia." (PMID 15823208, 2005). "Taken together, our data indicate that IL-9 may have some degree of regulatory effect on eosinophilia in the bone marrow and blood, perhaps via eosinophilopoiesis, since newly produced eosinophils were reduced in these compartments." (PMID 15823208, 2005). "Anti-IL-9 treatment reduced bone marrow eosinophilia with significant effect on mature eosinophils." (PMID 15823208, 2005). "Furthermore, the IL-9 concentration correlated positively with eosinophilia." (PMID 28934137, 2017). "In a recent study, an anti-IL-9 antibody significantly reduced bone marrow eosinophilia in an animal model; IL-9 was over-expressed in bone marrow CD4+ cells after allergen exposure, suggesting that IL-9 may participate in the regulation of granulocytopoiesis in allergic inflammation." (PMID 27053925, 2016).
eosinophilia (continued). "Furthermore, immunization of mice with IL-9-OVA complex, which leads to production of IL-9-neutralizing antibodies in treated animals, results in impaired parasite expulsion and decreased blood eosinophilia further indicating an important role for this cytokine in promoting resistance to T. muris." (PMID 23053395, 2012). "The monoclonal anti-IL-9 antibody, given at a dose of 100 μg before allergen exposure, did not significantly reduce allergen-induced airway eosinophilia, but consistently reduced bone marrow eosinophilia, by a reduction of newly produced (BrdU+) and mature bone marrow eosinophils." (PMID 15823208, 2005). "Despite the lack of effect of inhibition of airway eosinophilia by anti-IL-9, we consistently observed an inhibitory effect of the treatment on the increase in bone marrow eosinophils after allergen exposure." (PMID 15823208, 2005). "Importantly, our finding of no or limited inhibitory effect of BAL eosinophilia by anti-IL-9 is in agreement with a report showing that sensitized IL-9KO mice respond with normal airway inflammation after allergen exposure." (PMID 15823208, 2005).
inflammatory bowel disease (22 papers, 2016 to 2026). A spectrum of small and large bowel inflammatory diseases of unknown etiology. "Elevated IL-17 and IL-9/mast cell signaling have been associated with C. albicans pathogenicity during inflammatory bowel disease and celiac disease, respectively." (PMID 39347572, 2024). "Recent studies suggest that Th9 cells and their secretory cytokine IL-9 can also promote inflammatory bowel disease (IBD), which poses a significant risk factor for colon cancer development." (PMID 29881387, 2018). "For instance, Th9 cells contribute to inflammatory bowel disease by secreting IL-9, which damages the intestinal epithelial barrier." (PMID 40948790, 2025). "Activated Atg3- and Atg5-deficient T cells differentiated in vitro into TH9 cells show increased production of IL-9 compared to their WT counterparts, and mutations in core autophagy genes increase the risk for development of inflammatory bowel disease (IBD) in humans." (PMID 37708826, 2023). "Studies in patients with inflammatory bowel disease report that increased IL-9 serum protein concentration correlated with a less favourable prognosis and increased disease severity." (PMID 34224495, 2022). "However, there has been renewed interest in the role of IL-9 in other chronic inflammatory or autoimmune conditions, including lupus nephritis, inflammatory bowel disease, and endometriosis." (PMID 39766252, 2024). "Moreover, it was reported that an elevation of circulating IL-9 in patients with inflammatory bowel disease and correlate to a severe prognosis." (PMID 30369485, 2018). "In the gut inflammation in inflammatory bowel diseases (IBD), IL-9-producing CD4+ T cells were found to be colitogenic, as gut epithelial cells of ulcerative colitis patients expressed elevated levels of IL-9R." (PMID 29867972, 2018).
Arthritis (21 papers, 2012 to 2025). Inflammation of a joint. "In a mouse arthritis model, a reduction of ILC2 accumulation in the arthritic joint of IL-9−/− mice was associated with delayed resolution of arthritis." (PMID 32051038, 2020). "Furthermore, Th9 cells have been shown to promote the resolution of arthritis in animal models highlighting the importance of Th9 cells and IL-9 in resolving inflammation associated with RA." (PMID 40565964, 2025). "Key type 2 cytokines, like interleukin (IL)-4 and IL-13, but also others such as IL-5, IL-9, IL-25, and IL-33, exert regulatory properties on arthritis, dampening inflammation and inducing resolution of joint swelling." (PMID 35163028, 2022). "A recent study discovered that ILC2s are one of the major sources of IL-9 production in arthritis, and that they regulate the resolution of arthritis." (PMID 35163028, 2022). "Highest IL-9 levels >6000 pg/ml were found in the two RA patients with highly active arthritis, whereas IL-9 concentrations of moderate and low DAS28 activity stayed in the range of concentrations determined in HD (data not shown)." (PMID 33995403, 2021). "In a mouse model of arthritis, IL-9-producing ILC2s play a crucial role in the activation of Treg cells in mice and humans." (PMID 32403291, 2020). "Overexpression of IL-9 completely reconstituted ILC2s and accelerated the resolution of K/BxN serum-induced arthritis." (PMID 32051038, 2020). "Mice treated with acarbose significantly reduced IL-9 (P < 0.05) and IL-6 (P < 0.001) while miglitol reduced IL-9 (P < 0.05) compared with mice gavaged with water alone in the protocol of treatment starting before arthritis induction." (PMID 32116681, 2019). "Similarly, IL-9-/- mice treated with type II collagen demonstrated reduced joint swelling, and IL-9R-/- mice treated with type II collagen showed decreased arthritis severity and fewer swollen joints." (PMID 40771819, 2025). "IL-9(+) ILC2s promote the resolution of arthritis by interfering with regulatory T cells (Tregs)." (PMID 35163028, 2022). "IL-9 treatment can promote ILC2-dependent Treg activation and effectively reduce inflammation, which may explain the unique role of IL-9 in arthritis." (PMID 34177881, 2021). "This may suggest a more pronounced role of Th9 or IL-9 in highly active arthritis in inflamed joint structures." (PMID 33995403, 2021). "Furthermore, IL-9 has been proposed to induce the resolution of inflammation in arthritis by promoting type 2 innate lymphoid cell (ILC2) -dependent Treg activation." (PMID 33801620, 2021). "Therefore, IL-9-mediated ILC2 activation is essential for the resolution process by Treg cells in arthritis." (PMID 32403291, 2020). "In this model, E. lenta exacerbated arthritis severity by enhancing the immune response to type II collagen, which led to increased levels of pro-inflammatory cytokines in the serum, including interleukin (IL)-9, IL-17, IL-23, interferon (IFN)-γ and tumor necrosis factor (TNF)-α." (PMID 41431641, 2025). "Thus, our results may underestimate the true effect of Th9-inducing stimuli or of IL-9 in autoimmune inflammation in arthritis." (PMID 33995403, 2021). "Regarding IL-9, the direct functional proof is still restricted to murine data showing the importance of IL-9-driven ILC2 stimulation for the maintenance of lung homeostasis as well as for the resolution of arthritis." (PMID 32655549, 2020). "Patients with psoriatic arthritis (PsA) had higher serum levels of IL-9 than those without arthritis." (PMID 40771819, 2025). "They observed statistically significant reduced levels of IL-9 in patients with psoriatic arthritis compared to patients without arthritis." (PMID 40699767, 2025). "Antigen-induced arthritis, which represents a self-limited arthritis model, becomes highly chronic in the absence of IL-9, while IL-9 overexpression effectively induces the resolution of arthritis in chronic models." (PMID 30111884, 2018).
Arthritis (continued). "A recent elegant paper led by Rauber 116 showed that RA patients in remission had increased ILC2 producing IL‐9 in circulation and synovium, and that ILC2/IL‐9 fostered the resolution of inflammation and restored joint immune‐homeostasis in experimental arthritis models." (PMID 29315512, 2018). "Another cytokine not described in arthritis but known for its cell proliferation capacities, IL-9, was expressed early in sensitized knees." (PMID 22414623, 2012). "Based on the observation that antigen-induced arthritis did not spontaneously resolve in Il9−/− mice, the authors investigated whether an IL-9 producing population was critical for the resolution process." (PMID 30454038, 2018). "The levels of IL-3, IL-5, IL-9, and LIF, as well as those of GM-CSF and VEGF, did not increase in the setting of CFA-induced arthritis." (PMID 36293292, 2022).
colon carcinoma (18 papers, 2017 to 2025). "Colon cancer patients show a strong correlation between IL-9 expression and disease progression, with the better prognosis shown by patients with the highest levels of IL-9 in cancer tissues." (PMID 39281678, 2024). "The overexpression of IL-9 in a murine colon cancer CT26 model led to the transformation of the tumor microenvironment and delayed tumor growth." (PMID 38473379, 2024). "In human cancers, IL-9-producing cells have been detected in a growing list of malignancies including breast, lung, and colon cancer." (PMID 37189417, 2023). "Consistently, immunofluorescence analysis demonstrated a significant increase of mucosal IL-9-expressing T cells in colonic tumours, indicating the presence of IL-9 and Th9 cells." (PMID 35793807, 2022). "IL-9 also exerts a strong antitumor response in colon cancer, and the expression level of IL-9 in colon cancer is positively correlated with TNM stage, lymph node metastasis, and good prognosis." (PMID 32228589, 2020). "IL-9 also exerts a strong anti-tumor response in colon cancer." (PMID 34944921, 2021). "Interestingly, Tian and colleagues show that IL-9 expression in colitis-associated cancer tissue is significantly higher than that in adjacent tissues, and Lentiviral vector–mediated IL-9 overexpression in the colon cancer cells lines RKO and Caco2 could promote their proliferation." (PMID 33488574, 2020). "Moreover, an ectopically expressed membrane-bound form of IL-9 induces an immunostimulatory effect that suppresses the growth of CT26 colon cancer cells." (PMID 31637216, 2019). "In this setting, the importance of TH9 cell responses in mediating anti-tumor immunity following vaccination of CEA transgenic mice was shown by demonstrating that IL-9 neutralization prevents the ability of the vaccine to protect mice against a challenge of live colon carcinoma MC38.CEA cells." (PMID 27832300, 2017). "Notably, IL-9 quantification by immunohistochemistry and quantitative real-time PCR in tissue specimens of colon cancer patients showed a strong correlation between IL-9 expression and disease progression, with the better prognosis shown by patients with the highest levels of IL-9 in cancer tissues." (PMID 34944921, 2021). "Previous studies have shown that IL-9 has the ability to stimulate cell proliferation, so it is not surprising that IL-9 plays certain roles in allergic inflammation, tumorigenesis and the development of cancers such as lung, breast, thyroid, and colon cancer." (PMID 36936961, 2023). "Lentiviral vector-mediated IL-9 overexpression in the colon cancer cells lines RKO and Caco2 could promote the proliferation of colon cancer cells by upregulating the expression of c-myc and cyclin D1." (PMID 32228589, 2020).
lung carcinoma (18 papers, 2016 to 2025). "Apart from Th1 cells, other subpopulations, in particular Th9 cells (producing IL-9 and IL-21) and Th17 cells (producing IL-17), have been implicated in lung cancer." (PMID 36776832, 2023). "Next, we wanted to investigate the underlying mechanism of IL-9-mediated lung macrophage function in lung cancer." (PMID 35778404, 2022). "The functional relevance of IL-9 signaling in lung cancer was underlined by studies in several independent murine NSCLC models of lung adenocarcinoma where IL-9 deficiency resulted in suppression of tumor growth." (PMID 35514957, 2022). "Here, we show that IL-9 signaling is associated with poor outcomes in patients with various forms of lung cancer, and is required for lung tumor growth in multiple mouse models." (PMID 35778404, 2022). "In lung cancer, IL-9 can promote the migration of A549 cells through an ICAM/LFA-1– and/or VCAM-1/Integrin-β–dependent mechanism." (PMID 41302515, 2025). "The authors suggested IL-9 as a potential therapeutic agent to be combined with PD-1 blockade for treating lung cancer immunotherapeutically." (PMID 39325360, 2025). "Our findings provide new insights into the regulatory role of IL-9 for lung cancer growth and suggest new avenues for therapy of NSCLC by targeting of IL-9 function." (PMID 35514957, 2022). "Mechanistically, a recent study showed that Th9-derived IL-9 directly promoted both human and mouse lung cancer cell migration and proliferation." (PMID 35778404, 2022). "Further studies on the effects of IL-9 blockade in experimental lung cancer identified direct effects of IL-9 on tumor cells." (PMID 35514957, 2022). "Lung cancer patients also showed increased concentrations of serum IL-9, IL-6, and enhanced arginase activity." (PMID 35778404, 2022). "We next asked if the presence of IL-9 affects tumor development in a second syngenic model of lung cancer after intravenous injection of L1C2 lung tumor cell line in a Balb/c genetic background." (PMID 35514957, 2022). "Together, these results strongly suggest the IL-9-macrophage-Arg1 axis is correlated with the development of human lung cancer." (PMID 35778404, 2022). "High expression of IL9 and IL9R clearly associated with poor survival probability in lung cancer patients." (PMID 35778404, 2022). "IL-9 also inhibited the apoptosis and promoted the migration and adhesion abilities of lung cancer cells." (PMID 32508847, 2020). "Co-injection of LLC1 cells and Th9 cells promoted lung cancer growth and metastasis in Rag1−/− mice, whereas neutralization of IL-9 reversed these effects." (PMID 32508847, 2020). "Moreover, IMs represent the primary responders to IL-9 in lung cancer, and blocking IL-9 signaling on lung macrophages restricts the growth of murine lung tumors." (PMID 39026681, 2024). "Our results suggest IMs are the major IL-9 responsive cells in the context of lung cancer." (PMID 35778404, 2022). "Altogether, these results indicate that IL-9 signaling in macrophage could be a promising therapeutic target for lung cancer and potentially in other inflammatory lung diseases." (PMID 35778404, 2022). "As IL-10 and TGF-beta expressing T cells are known to play a crucial role for inducing Foxp3+ T regulatory cells and controlling immune responses in NSCLC, these results suggest that IL-9 plays an important role in regulating immune responses in lung cancer in vivo." (PMID 35514957, 2022). "Taken together, our findings indicate effects of IL-9 on growth of lung cancer cells." (PMID 35514957, 2022). "Thus, our study suggests the IL-9/macrophage/Arg1 axis is a potential therapeutic target for lung cancer therapy." (PMID 35778404, 2022). "Thus, our study advances the current understanding of IL-9-mediated disease development and provides a rationale for therapeutically targeting the IL-9-lung macrophage axis in patients with lung cancer." (PMID 35778404, 2022).